RPA3 (replication protein A3)
Description:
As part of the heterotrimeric replication protein A complex (RPA/RP-A), binds and stabilizes single-stranded DNA intermediates that form during DNA replication or upon DNA stress. It prevents their reannealing and in parallel, recruits and activates different proteins and complexes involved in DNA metabolism. Thereby, it plays an essential role both in DNA replication and the cellular response to DNA damage. In the cellular response to DNA damage, the RPA complex controls DNA repair and DNA damage checkpoint activation. Through recruitment of ATRIP activates the ATR kinase a master regulator of the DNA damage response. It is required for the recruitment of the DNA double-strand break repair factors RAD51 and RAD52 to chromatin, in response to DNA damage. Also recruits to sites of DNA damage proteins like XPA and XPG that are involved in nucleotide excision repair and is required for this mechanism of DNA repair. Also plays a role in base excision repair (BER), probably through interaction with UNG. RPA stimulates 5'-3' helicase activity of BRIP1/FANCJ. Also recruits SMARCAL1/HARP, which is involved in replication fork restart, to sites of DNA damage. May also play a role in telomere maintenance. RPA3 has its own single-stranded DNA-binding activity and may be responsible for polarity of the binding of the complex to DNA. As part of the alternative replication protein A complex, aRPA, binds single-stranded DNA and probably plays a role in DNA repair. Compared to the RPA2-containing, canonical RPA complex, may not support chromosomal DNA replication and cell cycle progression through S-phase. The aRPA may not promote efficient priming by DNA polymerase alpha but could support DNA synthesis by polymerase delta in presence of PCNA and replication factor C (RFC), the dual incision/excision reaction of nucleotide excision repair and RAD51-dependent strand exchange.
Synonyms: RP-A p14; REPA3
Tractability: Small molecule: a structure with a bound ligand is known; it has a binding pocket of medium quality. PROTAC: UniProt records ubiquitination sites on it; ubiquitination databases record sites on it; its protein half-life has been measured.
Gene: Protein-coding gene on chromosome 7 (7,634,843 to 7,718,607, reverse strand). Ensembl gene ENSG00000106399.
Subcellular location: Nucleus
Pathways (Reactome):
DNA Repair: Dual Incision in GG-NER; Dual incision in TC-NER; Fanconi Anemia Pathway; Formation of Incision Complex in GG-NER; Gap-filling DNA repair synthesis and ligation in GG-NER; Gap-filling DNA repair synthesis and ligation in TC-NER; HDR through Homologous Recombination (HRR); HDR through Single Strand Annealing (SSA); PCNA-Dependent Long Patch Base Excision Repair; Presynaptic phase of homologous DNA pairing and strand exchange; Processing of DNA double-strand break ends; Recognition of DNA damage by PCNA-containing replication complex; Termination of translesion DNA synthesis; Translesion Synthesis by POLH; Translesion synthesis by POLI; Translesion synthesis by POLK; Translesion synthesis by REV1
Cell Cycle: Activation of ATR in response to replication stress; G2/M DNA damage checkpoint; Removal of the Flap Intermediate from the C-strand
Cellular responses to stimuli: HSF1 activation; Regulation of HSF1-mediated heat shock response
DNA Replication: Activation of the pre-replicative complex; Removal of the Flap Intermediate
Disease: Impaired BRCA2 binding to RAD51
Reproduction: Meiotic recombination
Gene Ontology:
Molecular function: damaged DNA binding; protein binding; single-stranded DNA binding; DNA binding
Biological process: base-excision repair; DNA repair; DNA replication; double-strand break repair via homologous recombination; mismatch repair; nucleotide-excision repair; telomere maintenance; DNA recombination
Cellular component: DNA replication factor A complex; nucleus; nucleoplasm; site of double-strand break
Genetic constraint (gnomAD): Loss-of-function variants: 10 observed, 4.85 expected, observed/expected ratio (o/e) 2.06. That is too few expected variants to judge how well the gene tolerates losing a copy. Missense variants: 115 observed, 89.11 expected, observed/expected ratio (o/e) 1.29, 90% interval 1.11 to 1.51. Synonymous variants: 47 observed, 33.06 expected, observed/expected ratio (o/e) 1.42, 90% interval 1.12 to 1.79.
Homologues: Orthologues: chimpanzee RPA3 (98% identical), macaque RPA3 (94% identical), dog RPA3 (89% identical), dog RPA3 (88% identical), pig RPA3 (85% identical), rabbit RPA3 (84% identical), guinea pig RPA3 (83% identical), rat Rpa3l1 (79% identical), mouse Rpa3 (77% identical), tropical clawed frog rpa3 (60% identical), zebrafish rpa3 (57% identical).